COP1 (COP1 E3 ubiquitin ligase)
Description:
E3 ubiquitin-protein ligase that mediates ubiquitination and subsequent proteasomal degradation of target proteins. E3 ubiquitin ligases accept ubiquitin from an E2 ubiquitin-conjugating enzyme in the form of a thioester and then directly transfers the ubiquitin to targeted substrates. Involved in JUN ubiquitination and degradation. Probably mediates E3 ubiquitin ligase activity by functioning as the essential RING domain subunit of larger E3 complexes. In contrast, it does not constitute the catalytic RING subunit in the DCX DET1-COP1 complex that negatively regulates JUN, the ubiquitin ligase activity being mediated by RBX1. Involved in 14-3-3 protein sigma/SFN ubiquitination and proteasomal degradation, leading to AKT activation and promotion of cell survival. Ubiquitinates MTA1 leading to its proteasomal degradation. Upon binding to TRIB1, ubiquitinates CEBPA, which lacks a canonical COP1-binding motif (Probable).
Synonyms: RFWD2; RNF200; FLJ10416; FAP78; CFAP78
Tractability: PROTAC: UniProt records ubiquitination sites on it; ubiquitination databases record sites on it.
Target class: Enzyme; Transferase
Gene: Protein-coding gene on chromosome 1 (175,944,828 to 176,207,510, reverse strand). Ensembl gene ENSG00000143207.
Subcellular location: Nucleus speckle; Cytoplasm
Pathways (Reactome):
Cell Cycle: Autodegradation of the E3 ubiquitin ligase COP1
Metabolism of proteins: Neddylation
Gene Ontology:
Molecular function: protein binding; ubiquitin protein ligase activity; ubiquitin-protein transferase activity
Biological process: negative regulation of fatty acid biosynthetic process; positive regulation of proteasomal ubiquitin-dependent protein catabolic process; proteasome-mediated ubiquitin-dependent protein catabolic process; response to ionizing radiation; ubiquitin-dependent protein catabolic process; protein ubiquitination
Cellular component: Cul4A-RING E3 ubiquitin ligase complex; cytoplasm; cytosol; nucleoplasm; Golgi membrane; nuclear speck
Genetic constraint (gnomAD): Loss-of-function variants: 7 observed, 23.62 expected, observed/expected ratio (o/e) 0.3, 90% interval 0.17 to 0.56. The synonymous counts are far from expectation, so gnomAD's model fits this gene poorly and the ratio says little. Missense variants: 346 observed, 328.55 expected, observed/expected ratio (o/e) 1.05, 90% interval 0.96 to 1.15. Synonymous variants: 182 observed, 146.25 expected, observed/expected ratio (o/e) 1.24, 90% interval 1.1 to 1.41.
Homologues: Orthologues: chimpanzee COP1 (100% identical), macaque COP1 (99% identical), pig COP1 (98% identical), rat Cop1 (98% identical), mouse Cop1 (98% identical), rabbit COP1 (97% identical), guinea pig COP1 (95% identical), tropical clawed frog cop1 (85% identical), zebrafish cop1 (79% identical). Paralogues in human: WDR81 (24% identical), NWD1 (14% identical), MAPKBP1 (12% identical), WDR62 (12% identical), TEP1 (11% identical), WDR7 (8% identical), WDR75 (8% identical), AHI1 (7% identical), SNRNP40 (7% identical), WDR17 (7% identical), DAW1 (7% identical), WDR27 (6% identical), and 14 more.
Diseases named in the same sentence as COP1 in open-access papers:
COP1 is named in the same sentence as 81 diseases in open-access papers, as found by Europe PMC text mining. Sharing a sentence is not in itself a finding about the gene and the disease. The quoted sentences say what the papers report.
breast carcinoma (15 papers, 2010 to 2025). "In breast cancer cells, the depletion of COP1 resulted in the stabilization of the c-Jun protein and the subsequent enhancement of cancer cell growth/migration and in vivo metastasis." (PMID 36980717, 2023). "Transfection of cells with vectors encoding COP1 and constitutively activated GSK-3β resulted in decreased levels of c-JUN expression and the invasive breast cancer cells." (PMID 32365809, 2020). "The constitutive photomorphogenesis protein 1 (COP1) is an E3 ligase which was determined to be responsible for c-JUN degradation in less-invasive breast cancer cells." (PMID 32365809, 2020). "First of all, we observed COP1 and ETV1 expression status in several breast cancer cell lines, and found that breast cancer cell lines with relatively higher ETV1 expression displayed less COP1 abundance." (PMID 25884720, 2015). "COP1, another factor with a controversial effect in cancer, since it has been described both as involved in resistance to doxorubicin in leukemia cells and as a suppressor of breast cancer progression." (PMID 31331001, 2019). "In our cancer model study, COP1 knockdown inhibited tumor growth in xenograft breast cancer model." (PMID 26254224, 2015). "An inverse relationship was observed between COP1 and c-JUN in a panel of breast cancer cell lines." (PMID 32365809, 2020). "Increased expression of constitutive photomorphogenic 1 (COP1, also known as E3 ubiquitin protein ligase RFWD2), which contains WD40‐repeat domains, facilitates cell proliferation, transformation and cancer progression in human hepatocellular carcinoma, breast cancer and ovarian adenocarcinomas." (PMID 32394588, 2020). "However, compared to tumors with negative COP1 expression, positive COP1 expression was correlated with a significant decrease of breast cancer overall mortality during the follow-up period (log-rank test, P < 0.001)." (PMID 25884720, 2015).
hepatocellular carcinoma (11 papers, 2012 to 2026). A malignant tumor that arises from hepatocytes. "We have previously defined the constitutive photomorphogenic protein 1 (COP1) gene as a therapeutic target in hepatocellular carcinoma (HCC)." (PMID 41940593, 2026). "Downregulation of COP1 in hepatocellular carcinoma cells resulted in reduced proliferation and growth arrest and xenografts from these cells showed a dose-dependent decrease in tumor mass." (PMID 33670160, 2021). "Elevated COP1 levels were found in breast adenocarcinomas, ovarian adenocarcinomas, pancreatic cancer and hepatocellular carcinoma." (PMID 33670160, 2021). "Studies have shown that COP1, an E3-ubiquitin ligase, is overexpressed in human hepatocellular carcinoma (HCC)." (PMID 27398234, 2012).
acute myeloid leukemia (7 papers, 2019 to 2024). Acute myeloid leukemia (AML) is a group of neoplasms arising from precursor cells committed to the myeloid cell-line differentiation. "MiR-103 expression is upregulated in Adriamycin-resistant acute myeloid leukemia cells and confers K562 cells’ drug resistance via regulation of COP1 through PI3K/AKT signal pathway." (PMID 31372241, 2019). "TRIB2 may serve as an adaptor of the E3 ligase COP1 and inactivate C/EBPα in acute myelogenous leukemia." (PMID 34586732, 2021).
colorectal cancer (7 papers, 2014 to 2026). A primary or metastatic malignant neoplasm that affects the colon or rectum. "Moreover, computational analyses of drug response data in a large cancer cell line panel further supports that high DET1 or COP1 expression is correlated with low IC50 values (i.e., sensitivity) for five different MEK inhibitors across a colorectal cancer cell line panel." (PMID 30482246, 2018).
prostate carcinoma (6 papers, 2017 to 2023). A carcinoma that arises from epithelial cells of the prostate gland. "In prostate cancer, miR-424 targets E3 ubiquitin ligase COP1 to impair its function, thus activating STAT3 which is a key substrate of COP1 and promoting prostate tumor progression." (PMID 33033517, 2020). "Since both c-Jun and ETV are known as oncoproteins (especially in prostate cancer), COP1 has been suggested to act as a potential tumor suppressor gene." (PMID 30405104, 2018). "The protein dosage of PEA3 subfamily of ETS transcription factors ETV1, ETV4, and ETV5 is regulated through both transcription and ubiquitylation-mediated protein degradation by E3 ubiquitin ligase COP1, a tumor suppressor in both human prostate cancer and in GEM models of prostate cancer." (PMID 37018402, 2023). "Reasoning that the dosage of ETS protein is crucial in ETS-drive prostate cancer tumorigenesis, we created a low dosage (ETV4WT) level and a high dosage (ETV4AAA) level of ETV4 protein through increased ETV4 protein stability by mutating the conserved ExxVPD motifs responsible for COP1 degradation." (PMID 37018402, 2023). "miR-424-5p targeted E3 ligase COP1 to stabilize STAT3, thus promoting cell proliferation of prostate cancer cells." (PMID 34976194, 2022). "In conclusion, the current data suggested that MAGI2-AS3 acted as a sponge for miR-424-5p to elevate COP1 expression and inactivated STAT3 signaling in prostate cancer cells." (PMID 34976194, 2022). "Our data also showed that COP1 was upregulated and STAT3 was downregulated in prostate cancer cells with overexpression of MAGI2-AS3, moreover, the effects of MAGI2-AS3 on COP1 was reversed by miR-424-5p mimic." (PMID 34976194, 2022). "PDLIM2, Fbw7, and constitutive photomorphogenic 1 (COP1) were identified as E3 ligases for STAT3 in T helper 17 cells, diffuse large B-cell lymphoma (DLBCL) cells, and prostate cancer cells, and several proteins, including TMF/ARA160, are involved in proteasomal STAT3 degradation." (PMID 33859351, 2021).
gastric cancer (5 papers, 2020 to 2025). A primary or metastatic malignant neoplasm involving the stomach. "While Li and coworkers observed overexpression of COP1 in gastric cancer and an association of high COP1 levels with poor survival, Sawada and coworkers reported downregulation of COP1 in gastric cancer." (PMID 33670160, 2021). "CDH18 expression is upregulated when constitutive photomorphogenesis 1 (COP1) is silenced, which promotes gastric cancer development by failing to inhibit PI3K/AKT signaling." (PMID 40017628, 2025). "In recent years, the involvement of E3 ubiquitin ligase constitutive photomorphogenesis 1 (COP1) in the tumorigenesis of gastric cancer (GC) has been elucidated." (PMID 37025097, 2023). "For example, CDH18 was shown to inhibit invasion/migratory ability and chemoresistance via ubiquinol cytochrome c reductase core protein 2 (UQCRC2) in gliomas,and reduce malignancy in gastric cancer via the constitutive photomorphogenesis 1 (COP1)-PI3K/AKT pathway axis." (PMID 40017628, 2025).
melanoma (5 papers, 2014 to 2025). A malignant, usually aggressive tumor composed of atypical, neoplastic melanocytes. "We found that patient mutations in COP1 or DET1 inactivated CRL4COP1/DET1 in melanoma cells, stabilized ETV1, ETV4, and ETV5, and conferred resistance to inhibitors of the MAPK pathway." (PMID 40643496, 2025). "COP1 loss in A375 melanoma and GIST-T1 cell line-derived xenograft models led to increased ETV1 (and ETV4/5) levels and resistance to MAPK inhibitor treatments." (PMID 34066106, 2021). "These interactions suggest how modifying chondroitin sulfation can regulate activation of critical signaling pathways and affect ubiquitination through the expression of COP1, thereby leading to inhibition of melanoma growth." (PMID 40562100, 2025). "In this report, we present the signaling and transcriptional events initiated by arylsulfatase B (ARSB; N-acetylgalactosamine-4-sulfatase), which lead to COP1-mediated apoptosis of melanoma cells." (PMID 40562100, 2025). "The subsequent, enhanced FOXO3a nuclear effect on COP1 expression leads to apoptosis of the melanoma cells, consistent with the role of FOXO3a as a tumor suppressor." (PMID 40562100, 2025). "In this report, we address how treatment by recombinant human ARSB impacts on apoptosis of melanoma by COP1 and identify a pathway by which ARSB-induced changes in chondroitin sulfation regulate COP1 expression." (PMID 40562100, 2025). "De novo activity-attenuating DET1 mutations were identified in two melanoma patients after vemurafenib (RAF inhibitor) treatment, further implicating COP1/DET1 loss as a driver of MAPK inhibitor resistance." (PMID 34066106, 2021). "These associations between UV exposure, COP1, ETS1, BCL2, and melanoma apoptosis can provide new insight into fundamental melanoma pathophysiology, although no precise common mechanism between UVB exposure and decline in ARSB has been identified." (PMID 40562100, 2025). "COP1, which inhibits ultraviolet-B stimulated growth in plants, suppresses nuclear ETS1 and ETS1-mediated expression of BCL2 in the murine melanomas and in human melanoma cells." (PMID 40562100, 2025). "In human epidermal keratinocytes, silencing COP1 increased UVB-mediated transcriptional effects and UVB reduced COP1 expression, consistent with the inhibitory role of COP1 in melanoma detailed in this report, since human melanoma growth is stimulated by UVB exposure." (PMID 40562100, 2025). "The experiments in this report indicate that exogenous, bioactive rhARSB inhibits melanoma progression by stimulating apoptosis through effects of the E3 ubiquitin ligase constitutive photomorphogenic 1 (COP1; RFWD2), a known inhibitor of growth response to ultraviolet B (UVB) light." (PMID 40562100, 2025). "Transcriptional outputs arising from elevated ERK activity seen in BRAF V600-mutant melanomas and KIT-mutant gastrointestinal stromal tumours (GISTs) may also be mediated through ETV1 unconstrained by COP1." (PMID 34066106, 2021). "Inverse to the impact of exogenous ARSB and pertinent to the development of melanoma, ARSB silencing increased CHST15 expression, abundance of C4,6S disaccharides, and activation of phospho(Tyr)-ROR1 and phospho(Ser473)-AKT1 and reduced nuclear FOXO3a and COP1 expression." (PMID 40562100, 2025). "COP1, an E3 ubiquitin ligase, has been identified as a repressor of UVB-stimulated responses in plants and human cells but not previously considered in relation to melanoma apoptosis." (PMID 40562100, 2025).
lung carcinoma (4 papers, 2016 to 2025). "TRIB2 has previously been shown to function as an adaptor mediating the degradation of C/EBPα via COP1 E3 ligase in AML or TRIM21 E3 ligase in lung cancer, and these are likely candidates that link the TRIB2 pseudokinase domain to ubiquitination." (PMID 27563873, 2016). "For example, COP1 was reportedly overexpressed in HCC and decreased in lung cancer according to Oncomine datasets." (PMID 31670863, 2020).
cognitive deficit (3 papers, 2015 to 2026). "We suggest that future studies employ long-term cortical EEG recordings and other behavioral tasks to objectively assess whether Cop-1/GA-induced neurogenesis causes seizures, epilepsy or cognitive deficit." (PMID 25821957, 2015).
colon cancer (3 papers, 2017 to 2023). "Analysis of TCGA, GTEx, and GEO databases revealed that COP1 mRNA expression was upregulated in colon cancer or adenomas compared to normal colon tissues." (PMID 37679762, 2023). "More interestingly, co-expression of 14-3-3σ reverses COP1-promoted tumorigenicity in a xenograft mouse model of colon cancer." (PMID 28218667, 2017). "To examine and confirm the relationship among CSN6, COP1, and FOXO4 in human cancers, we performed IHC staining on a tissue microarray (TMA) from our human colon cancer cohort to assess the expression of these proteins." (PMID 33101846, 2020).
liver cancer (3 papers, 2021 to 2026). An epithelial or non-epithelial malignant neoplasm that arises from the liver. "Furthermore, TRIB2 has been revealed to interact with E3s including Smurf1, COP1, and βTrCP in liver cancer cells." (PMID 34315867, 2021). "Targeting of COP1 reduced fat accumulation and metastatic potential in both HCC parental cells and CD133+ liver cancer stem cells." (PMID 41940593, 2026).
ovarian carcinoma (3 papers, 2021 to 2024). A malignant neoplasm originating from the surface ovarian epithelium. "Here, our data identify that COP1 is a new KAT6A substrate, which advanced our knowledge of the function of KAT6A and COP1 and their association with ovarian cancer." (PMID 33995658, 2021). "In summary, our work provides new insights into the posttranslational modification of COP1 and β-catenin in ovarian cancer and highlights that KAT6A functions as an acetyltransferase of nonhistone proteins, by which KAT6A is implicated in tumor progression." (PMID 33995658, 2021). "We further determine how COP1 acetylation contributes to the progression of ovarian cancer as an E3 ubiquitin ligase." (PMID 33995658, 2021). "β-catenin has been reported to be a substrate of COP1 28-29 and immoderate activation of Wnt/β-catenin signaling is involved in many malignancies, including ovarian cancer." (PMID 33995658, 2021). "We then mutated K294 of COP1 to arginine (K294R, acetylation-dead mutant), which significantly impaired KAT6A-induced acetylation of COP1 in ovarian cancer cells." (PMID 33995658, 2021). "COP1 (also called RFWD2) is an E3 ubiquitin ligase that has been reported to be overexpressed in ovarian cancer." (PMID 33995658, 2021). "It binds to and acetylates COP1 at K294, which impairs the function of COP1 as an E3 ubiquitin ligase and leads to the accumulation and enhanced activity of β-catenin, thereby promoting the proliferation and migratory ability of ovarian cancer cells." (PMID 39253578, 2024). "Moreover, KAT6A, acting as a regulator of β-catenin, promotes the proliferation, invasion and metastasis of ovarian cancer cells and endows them with resistance to platinum-based chemotherapeutics by acetylating constitutive photomorphogenic 1 (COP1)." (PMID 33995658, 2021). "Therefore, we concluded that KAT6A could promote activation of the Wnt/β-catenin pathway by acetylating COP1 and further promote tumorigenesis, cancer invasion and chemoresistance in ovarian cancer." (PMID 33995658, 2021). "KAT6A‐ΔIDR also induced resistance to cisplatin treatment by acetylating COP1 and stabilizing β‐catenin, similar to KAT6A‐WT in ovarian cancer cells." (PMID 38973255, 2024). "Taken together, these results demonstrate that the acetylation of COP1 by KAT6A stabilizes β-catenin by impairing β-catenin ubiquitination, resulting in the abnormal activation of the β-catenin signaling pathway and promoting the proliferation and metastasis of ovarian cancer cells." (PMID 33995658, 2021).
angiosarcoma (2 papers, 2015 to 2024). A malignant tumor arising from the endothelial cells of the blood vessels.